GREM1 (gremlin 1, DAN family BMP antagonist)
Diseases named in the same sentence as GREM1 in open-access papers (continued):
Sharing a sentence is not in itself a finding about the gene and the disease.
hypospadias (2 papers, 2021 to 2025). Hypospadias is the displacement of the urethral meatus on the ventrum of the penis. "In summary, GREM1 risk allele rs3743104[G] increase susceptibility to hypospadias in mild/moderate and severe cases from the Southern Han Chinese population and regulates GREM1 expression by altering the binding affinity of miR-182 to their locus." (PMID 33962391, 2021). "As a member of the bone morphogenic protein antagonist family, GREM1 has been identified as associated with susceptibility to hypospadias in the European population." (PMID 33962391, 2021). "Stratification analysis for the association between GREM1 risk allele rs3743104[G] and hypospadias susceptibility (by subgroup)." (PMID 33962391, 2021). "Collectively, this study provides new evidence that GREM1 rs3743104 is associated with an increased risk of hypospadias." (PMID 33962391, 2021). "This is the largest Chinese population-based study to examine the correlation of GREM1 genetic polymorphisms with hypospadias risk, enrolling 557 cases and 645 unrelated controls." (PMID 33962391, 2021). "They reported that rs3743104 could affect the binding of miR-182 to GREM1, potentially increasing the risk of developing hypospadias." (PMID 39624466, 2025). "Association between GREM1 polymorphism rs3743104 and hypospadias susceptibility." (PMID 33962391, 2021). "Nevertheless, the biological mechanism underlying the correlation between GREM1 polymorphism and hypospadias sensitivity remains unclear." (PMID 33962391, 2021). "In this study, the associated of GREM1 rs3743104 with hypospadias was replicated." (PMID 33962391, 2021). "GREM1 is recognized as part of the bone morphogenic protein antagonist family (BMP), and has been linked to susceptibility to hypospadias." (PMID 39624466, 2025). "Third, in-depth analyses are warranted to explore the biological mechanisms of GREM1 rs3743104 and hypospadias sensitivity." (PMID 33962391, 2021). "Further studies are required to understand the biological mechanism by which variations in GREM1 contribute to the pathogenesis of hypospadias." (PMID 33962391, 2021). "We also further demonstrated the functional relevance of GREM1 rs3743104 on Hypospadias and the mechanism of the SNP-related MicroRNAs(miRNA) involved in regulating GREM1 expression." (PMID 33962391, 2021). "Furthermore, the interaction of miR-182 with GREM1 suggests its potential role in hypospadias progression through the bone morphogenic protein (BMP) signaling pathway, which is known to be involved in urethral development." (PMID 39624466, 2025). "The relationship between GREM1 and subtypes of hypospadias was studied." (PMID 33962391, 2021). "Given that rs3743104 is located at the 3′-UTR of GREM1, we provided a series of experimental evidence showing that rs3743104 has a regulatory effect on the expression of upstream GREM1, which thereby might contribute to the progression of Hypospadias." (PMID 33962391, 2021).
Incisional hernia (2 papers, 2013 to 2019). An abdominal hernia that occurs at a site of weakness in the abdominal wall resulting from an incompletely-healed surgical wound. "They revealed an association between GREM1, a bone morphogenetic protein antagonist 1, and incisional hernia formation." (PMID 31024927, 2019). "Interestingly, our data showed that FST-like 1 expression accompanied GREM1 expression in the skin of recurrent incisional hernia patients." (PMID 22648066, 2013).
intestinal cancer (2 papers, 2024 to 2025). "Through bioinformatics analysis, we explored that PI3K/AKT pathway is a possible downstream pathway of miR-455/GREM1 axis, which plays an important role in the process of liver metastasis of intestinal cancer." (PMID 38970064, 2024). "Bioinformatics analysis shows that miR-455/GREM1 axis plays crucial role in liver metastasis of intestinal cancer and predicts its possible mechanism." (PMID 38970064, 2024).
intestinal polyp (2 papers, 2025). Discrete abnormal tissue masses that protrude into the lumen of the intestine. "A mouse model of HMPS with aberrant GREM1 overexpression in intestinal epithelial cells recapitulated this proliferative phenotype, suggesting that high levels of GREM1 alone can drive intestinal cell growth, intestinal polyp, and tumor formation." (PMID 41033552, 2025).
lymph node metastasis (2 papers, 2019 to 2020). "The expression of miR-137 in patients without lymph node metastasis was elevated versus patients with lymph node metastasis (p < 0.05), while its correlation with the expression of GREM1 was inverse." (PMID 31143092, 2019).
renal carcinoma (2 papers, 2020). A carcinoma arising from the epithelium of the renal parenchyma or the renal pelvis. "Of these, several genes including CASP5, RAP1GAP, and GREM1 have been reported to be involved in the pathogenesis of renal cancer or significant in predicting overall survival, suggesting that the present analysis using the TCGA database has potential prognostic value." (PMID 32952743, 2020).
scleroderma (2 papers, 2016 to 2025). Scleroderma is a rare autoimmune connective tissue disorder characterized by abnormal hardening of the skin and, sometimes, other organs. "Given that GREM1+ and PLA2G2A+ fibroblasts are observed in both CLE and scleroderma, another autoimmune skin disease with mucin deposition, we examined mucin-associated gene expression across fibroblast populations." (PMID 40409678, 2025).
scoliosis (2 papers, 2020 to 2022). A congenital or acquired spinal deformity characterized by lateral curvature of the spine. "MiR-151a-3p may contribute to scoliosis progression through the inhibition of GREM1 gene expression in osteoblasts interrupting bone homeostasis." (PMID 35682604, 2022). "The overexpression of miR-151a-3p may contribute to the progression of scoliosis via inhibition of GREM1 expression in osteoblasts to interrupt bone homeostasis." (PMID 33029507, 2020).
silicosis (2 papers, 2022 to 2025). Silicosis is a respiratory disease caused by breathing in (inhaling) silica dust. "A recent study in a silica-induced mouse silicosis model has identified a class of inflammatory proliferative fibroblasts characterized by high GREM1 expression." (PMID 41007698, 2025). "Inflammatory-proliferative fibroblasts play a key role in the early pathological changes that occur in silicosis, and during this process, GREM1 is the driving factor that targets PPP2R3A and initiates the inflammatory response, which is followed by irreversible fibrosis induced by SiO2." (PMID 35933397, 2022). "The GREM1/PPP2R3A pathway may be a potential target in the early treatment of silicosis." (PMID 35933397, 2022).
squamous cell carcinoma (2 papers, 2017 to 2020). A carcinoma arising from squamous epithelial cells. "Together, these observations suggested that GREM1 production by fibroblasts might induce a more aggressive malignant cell behavior in adenocarcinoma but not squamous cell carcinoma." (PMID 32381040, 2020).
ulcers (2 papers, 2021 to 2023). "Strikingly,Grem1 expression was upregulated in the muscularismucosa/propria of the ulcer environs as early as 5 hours after injury andpersisted to at least day 6 after wounding." (PMID 33819486, 2021).
viral infection (2 papers, 2019 to 2025). "Although the TGFβ2 factor, recently recognized as a key factor in fibrosis induction, did not result upregulated by virus infection in HUVECs, other factors belonging to TGFβ superfamily were promoted in particular by HHV-6A, including GREM1 and INHBE, IL-4, IL-5, TNF, and MMP9." (PMID 31878218, 2019).
Anxiety (1 paper, 2021). Intense feelings of nervousness, tension, or panic often arise in response to interpersonal stresses. "Both of the exploratory behavior tests indicated that conditional loss of Grem1 leads to reduced anxiety-like behavior." (PMID 34184027, 2021).
benign skin tumors (1 paper, 2017). "Among benign skin tumors, only PMCs showed high levels of GREM1 expression, probably due to the underlying inflammation." (PMID 28346486, 2017). "Among benign skin tumors, only PMCs (9 cases, 90%) showed GREM1 positivity." (PMID 28346486, 2017). "In addition, GREM1 expression in the stromal cells of benign skin tumors and of other malignant tumors such as SCCs and MNs is unknown." (PMID 28346486, 2017).
Cirrhosis (1 paper, 2021). A chronic disorder of the liver in which liver tissue becomes scarred and is partially replaced by regenerative nodules and fibrotic tissue resulting in loss of liver function. "Additionally, miR-4793-3p has been reported to be upregulated in patients with cirrhosis, and plays a role in the innate immune response by binding with Grem1 to suppress the TGF-β signaling pathway." (PMID 34354043, 2021).
coloboma (1 paper, 2018). An abnormality in which a part of a structure in one or both eyes is missing. "Thus, it is not surprising that the loss of a single BMP antagonist does not result in coloboma (Grem1 mutant mice)." (PMID 29593116, 2018).
craniosynostosis (1 paper, 2021). Craniosynostosis is defined as the premature fusion of one or more cranial sutures leading to secondary distortion of skull shape resulting in skull deformities with a variable presentation. "We show that asymmetric distribution of Erg and Six2 is lost in Twist1+/−;Tcf12+/− mutants, and in a companion study that similar asymmetric distribution of Grem1+ progenitors is lost in Tcf12−/− mutants, consistent with bones meeting end-on-end and fusing in these craniosynostosis models." (PMID 34376651, 2021).
Crohn disease (1 paper, 2024). A gastrointestinal disorder characterized by chronic inflammation involving all layers of the intestinal wall, noncaseating granulomas affecting the intestinal wall and regional lymph nodes, and transmural fibrosis. "A study showed that Grem1+ Grem2+ myofibroblasts highly express COL18A1 and COL23A1 mRNA in the ileum of patients with Crohn’s disease." (PMID 39327633, 2024). "Myofibroblast reprogramming into Grem1+ Grem2+ cells is induced by CHMP1A, TBX3, and RNF168, which might contribute not only to wound healing but also fibrosis in Crohn’s disease." (PMID 39327633, 2024).
disc degeneration (1 paper, 2022). "Furthermore, using RT-qPCR, WB, and IHC to analyze an appropriate number of patient NP samples, we demonstrated that the expression level of Grem1 was positively correlated with the severity of disc degeneration." (PMID 35440754, 2022).
discoid lupus erythematosus (1 paper, 2025). A chronic, autoimmune skin condition that manifests with a red, scaling rash, most often found on the face, ears, and scalp; these lesions often lead to permanent scarring and dyspigmentation. "Importantly, these GREM1+ fibroblasts were consistently present across CLE subtypes, including both subacute cutaneous lupus (SCLE) and discoid lupus erythematosus (DLE), with the same localization, associated chemokines (CXCL10, CCL5), and associated cell types (pDC, T cells)." (PMID 40409678, 2025).
embryonal carcinoma (1 paper, 2008). A non-seminomatous malignant germ cell tumor characterized by the presence of large germ cells with abundant cytoplasm resembling epithelial cells, geographic necrosis, high mitotic activity, and pseudoglandular and pseudopapillary structures formation. "Grem1, a known BMP antagonist, enhanced DMSO-induced cardiomyogenesis of P19CL6 embryonal carcinoma cells (CL6 cells) 10–35 fold in an area of beating differentiated cardiomyocytes." (PMID 18545679, 2008).
Endotoxemia (1 paper, 2022). "Endotoxemia led to a significant decrease in the level of mRNA expression of HAS2, COX2 and GREM1 genes in cumulus cells." (PMID 34826885, 2022).
estrogen-receptor negative breast cancer (1 paper, 2019). "Importantly, high expression of GREM1 predicted poor prognosis in estrogen receptor negative breast cancer patients." (PMID 31694641, 2019).
Familial adenomatous polyposis (1 paper, 2025). Familial adenomatous polyposis (FAP) is characterized by the development of hundreds to thousands of adenomas in the rectum and colon during the second decade of life. "People with polyposis could have a genetic basis with germline mutations in polyposis-related genes, such as the APC gene, resulting in familial adenomatous polyposis (FAP), MUTYH-associated polyposis (MAP), or, rarely, in other genes such as AXIN2, GREM1, NTHL1, POLE, POLD1, or MSH3." (PMID 40095498, 2025).
glaucoma (1 paper, 2022). Increased pressure in the eyeball due to obstruction of the outflow of aqueous humor. "Examples of these include genetic models of glaucoma (MyocY437H mice), OHT induced by transduction of the TM with glaucoma-related genes (e.g., MYOC, TGFβ2, GREM1, CTGF, DKK1, SFRP1, CD44, Cre and inducible transgene models, genome editing), as well as glucocorticoid-induced OHT models." (PMID 35129590, 2022).
head and neck squamous cell carcinoma (1 paper, 2022). A squamous cell carcinoma that arises from any of the following anatomic sites: lip and oral cavity, nasal cavity, paranasal sinuses, pharynx, larynx, and salivary glands. "Head and neck squamous cell carcinoma (HNSCC) cell lines were cocultured with their patient-matched CAFs in 2D and 3D in vitro models, and GREM1 was upregulated." (PMID 35874760, 2022).
hereditary cancer (1 paper, 2018). Malignant neoplasms occurring in families at a rate greater than that expected by chance and caused by germline mutations in a specific gene.
hereditary intestinal polyposis (1 paper, 2025). An inherited form of intestinal polyps that include familial adenomatous polyposis and juvenile polyposis syndrome. "As we have demonstrated a role for GREM1 in remodelling the stromal microenvironment to generate an ectopic stem cell niche in a disease-positioned model of a hereditary intestinal polyposis, it would be interesting to explore whether this mechanism persists into established sporadic cancers." (PMID 40467544, 2025).
inflammatory bowel disease (1 paper, 2025). A spectrum of small and large bowel inflammatory diseases of unknown etiology. "Thus, we sought to elucidate the therapeutic effect of targeting delivery of Grem1 and IL-10 in SETD2-deficient and DSS-induced inflammatory bowel disease." (PMID 39990215, 2025).
leukemia (1 paper, 2025). A malignant (clonal) hematologic disorder, involving hematopoietic stem cells and characterized by the presence of primitive or atypical myeloid or lymphoid cells in the bone marrow and the blood. "Deficiency of GREM1 induces adipogenicity of BM‐MSCs, leading to the rapid proliferation of leukemia cells." (PMID 40285538, 2025). "We demonstrate a novel mechanism wherein GREM1 deficiency induces adipogenicity of BM‐MSCs, leading to the rapid proliferation of leukemia cells and a high risk of death after relapse." (PMID 40285538, 2025). "The deficiency of GREM1 induced adipogenicity through the BMP/SMAD pathway, thereby contributing to the proliferation of leukemia cells by increasing fatty acid uptake." (PMID 40285538, 2025).
lip (1 paper, 2026). "Immunohistochemistry (IHC) for MYH3, IRF6, and GREM1 proteins and chromogenic in situ hybridization (CISH) for IRF6 and GREM1 genes were used to analyze postnatal unilateral right cleft lip tissue (ten patients) and control tissue (six patients)." (PMID 42196143, 2026).
lung squamous cell carcinoma (1 paper, 2022). "The analysis from the GEPIA database presented the poor OS in multiple tumors as the high expression of GREM1 gene, such as the ACC, KIRC, lung squamous cell carcinoma (LUSC), PDAC, and uveal melanoma (UVM)." (PMID 36091126, 2022).
malignant skin tumors (1 paper, 2017). "In this study, we investigated the expression of GREM1 mRNAs in various benign and malignant skin tumors, including various BCC subtypes." (PMID 28346486, 2017). "In summary, we demonstrated that the GREM1- positive myofibroblasts appear in scar tissue and in invasive skin cancers, including BCCs, SCCs, and MNs." (PMID 28346486, 2017). "Next, we assessed the transcription levels of GREM1 in various benign and malignant skin tumors." (PMID 28346486, 2017). "Additionally, we found that other skin cancers such as SCCs and MNs harbor GREM1-positive CAFs." (PMID 28346486, 2017).
MELAS (1 paper, 2017). "Apart from many targets including PINK1, FOXO1, PPARγ and Apaf-1 investigated before, MKNK2, GREM1 and EEF1A1 that might be potential targets of miR-27b-3p were revealed in the regulatory network of MELAS pathogenesis." (PMID 28139706, 2017).
mucinous adenocarcinoma (1 paper, 2018). An invasive adenocarcinoma composed of malignant glandular cells which contain intracytoplasmic mucin. "Mice expressing Grem1 cDNA under the control of the villin promoter develop colonic polyposis including dysplastic serrated polyps, but no mucinous adenocarcinoma." (PMID 30323897, 2018).
myocardial inflammation (1 paper, 2024). "Overall, these data demonstrate that antibody-mediated GREM1/2 blockade efficiently ameliorates T cell-induced myocardial inflammation and loss of cardiomyocytes during the acute phase of myocarditis." (PMID 39196111, 2024).
oligoarticular JIA (1 paper, 2022). "LRRC15, GREM1, and GREM2 are overexpressed in chondrocyte-like cells from persistent oligoarticular JIA FLS compared to pre-extension oligoarticular JIA FLS." (PMID 36167601, 2022).
osteonecrosis (1 paper, 2021). A none disease characterized by death of bone tissue due to a lack of blood supply. "MiR-27a is downregulated and negatively correlated with PPARγ and gremlin 1 (GREM1) expression in steroid-induced osteonecrosis of femoral head patients." (PMID 34164391, 2021).
rectal cancer (1 paper, 2021). A primary or metastatic malignant neoplasm that affects the rectum. "To investigate the clinical significance of GREM1 and ISLR expression in CRC CAFs, we evaluated GREM1 and ISLR expression by ISH in 53 rectal cancer surgical samples." (PMID 33197448, 2021). "Survival analyses showed that high GREM1 expression (score of ≥3) and high ISLR expression (score of ≥2) were independent prognostic factors for poor and favorable disease-free survival, respectively, in patients with rectal cancer." (PMID 33197448, 2021).
renal tumors (1 paper, 2010). "Consistently, GREM1, the antagonist of BMP that signals through SMADs was highly up-regulated in mutant FLCN and FLCN-null UOK257 cells although its expression was low in BHD-associated renal tumors." (PMID 20573232, 2010). "GREM1, TGFB2, INHBA, THBS1 and SMAD3 RNA expression levels were significantly lower in the BHD renal tumors compared to normal kidney tissue." (PMID 20573232, 2010).
skin tumors (1 paper, 2017). "Therefore, in this study, we have used RNA ISH to investigate the stromal expression of GREM1 in various skin tumors, and compared the expression of GREM1 between benign and malignant tumors, and between the distinct BCC subtypes." (PMID 28346486, 2017). "To specifically identify GREM1-expressing cells, we performed RNA ISH on tissue microarrays containing various samples of skin tumors." (PMID 28346486, 2017). "None of the epithelial components of skin tumors included in this study showed GREM1 mRNA expression; GREM1 mRNA localized to the stromal fibroblasts only." (PMID 28346486, 2017).
teratocarcinoma (1 paper, 2008). A germ cell tumor characterized by the presence of an embryonal carcinoma component and a teratoma component. "In conclusion, we have demonstrated that Grem1 enhances the commitment or determined path to cardiogenic differentiation of CL6 teratocarcinoma cells." (PMID 18545679, 2008).